NPY5R (neuropeptide Y receptor Y5)
Description:
Receptor for neuropeptide Y and peptide YY. The activity of this receptor is mediated by G proteins that inhibit adenylate cyclase activity. Seems to be associated with food intake. Could be involved in feeding disorders.
Synonyms: NPY5-R; NPYY5-R; NPYR5
Tractability: Small molecule: a drug acting on it is in phase 2 or 3 trials; a high-quality ligand is known; it belongs to a druggable protein family. Antibody: its Gene Ontology location is reachable by antibodies, with high confidence; UniProt places it where antibodies can reach, with medium confidence; UniProt predicts a signal peptide or a membrane-spanning region. PROTAC: a small molecule that binds it is known.
Target class: Neuropeptide Y receptor; Peptide receptor (family A GPCR); Membrane receptor; Family A G protein-coupled receptor; Short peptide receptor (family A GPCR)
Chemical probes: CGP-71683A (high quality), CHEMBL257940, PD083576
Gene: Protein-coding gene on chromosome 4 (163,343,583 to 163,352,477, forward strand). Ensembl gene ENSG00000164129.
Subcellular location: Cell membrane
Pathways (Reactome):
Signal Transduction: G alpha (i) signalling events; Peptide ligand-binding receptors
Gene Ontology:
Molecular function: neuropeptide Y receptor activity; pancreatic polypeptide receptor activity; peptide YY receptor activity; G protein-coupled receptor activity
Biological process: cardiac left ventricle morphogenesis; outflow tract morphogenesis; chemical synaptic transmission; G protein-coupled receptor signaling pathway; neuropeptide signaling pathway; eating behavior; generation of ovulation cycle rhythm; negative regulation of acute inflammatory response to antigenic stimulus; negative regulation of apoptotic process; negative regulation of glutamate secretion; negative regulation of synaptic transmission, GABAergic; positive regulation of acute inflammatory response; positive regulation of cell population proliferation; positive regulation of ERK1 and ERK2 cascade; positive regulation of smooth muscle cell proliferation; response to ethanol; synaptic signaling via neuropeptide
Cellular component: neuron projection; plasma membrane; 9+0 non-motile cilium; GABA-ergic synapse; membrane; presynapse
Genetic constraint (gnomAD): Loss-of-function variants: 21 observed, 25.63 expected, observed/expected ratio (o/e) 0.82, 90% interval 0.58 to 1.18. The upper end of that interval is the gene's LOEUF score, 1.18, which puts it in group 5 of 6, group 1 being the genes least tolerant of losing a copy. Missense variants: 460 observed, 525.99 expected, observed/expected ratio (o/e) 0.87, 90% interval 0.81 to 0.94. Synonymous variants: 168 observed, 186.71 expected, observed/expected ratio (o/e) 0.9, 90% interval 0.79 to 1.02.
Homologues: Orthologues: chimpanzee NPY5R (100% identical), macaque NPY5R (99% identical), guinea pig NPY5R (96% identical), dog NPY5R (95% identical), rabbit NPY5R (91% identical), mouse Npy5r (89% identical), rat Npy5r (89% identical), pig NPY5R (85% identical), tropical clawed frog npy5r (70% identical), zebrafish npy4r (27% identical). Paralogues in human: NPY1R (24% identical), NPY2R (22% identical), NPY4R (22% identical), NPY4R2 (22% identical), PRLHR (21% identical), PROKR2 (19% identical), PROKR1 (19% identical), GPR83 (18% identical), TACR3 (17% identical), TACR2 (16% identical), MCHR1 (16% identical), TACR1 (15% identical), and 21 more.
Diseases named in the same sentence as NPY5R in open-access papers:
NPY5R is named in the same sentence as 25 diseases in open-access papers, as found by Europe PMC text mining. Sharing a sentence is not in itself a finding about the gene and the disease. The quoted sentences say what the papers report.
Obesity (6 papers, 2009 to 2022). Accumulation of substantial excess body fat. "Among these, regression analysis found four well-established obesity associated genes that were positively correlated (CPE, LEP, NPY1R, and NPY5R), and two genes (APOM, and CRP) that were negatively correlated with weight gain." (PMID 23544116, 2013). "Interestingly, a third group of genes (CPE, NPY5R, DRD3, TAS2R38, SLC18A1, G6PC3, NPY1R, and VLDLR) was highly associated with both neurological and obesity concepts." (PMID 23544116, 2013).
breast carcinoma (5 papers, 2020 to 2025). "NPY1R and NPY5R first gained relevance in breast cancer research because of their high abundance and density compared with all other NPYR-positive tumors." (PMID 37264315, 2023). "NPY1R and NPY5R stimulation promotes cellular proliferation, migration, and angiogenesis in breast cancer models." (PMID 37264315, 2023). "Here, we measured the effects of NPY1R and NPY5R antagonists in normoxia and hypoxia on migration, proliferation, invasion, and signaling in 2D and 3D models of breast cancer cell lines MDA-MB-231 and MCF7." (PMID 37264315, 2023). "However, it is unclear why NPY1R abundance is more strongly connected to outcome, which currently limits the clinical relevance of NPY5R expression levels in breast cancer." (PMID 37264315, 2023). "We investigated whether such analogs could antagonize NPY1R and NPY5R to influence cancer hallmarks in two different breast cancer cell lines while considering the effects of hypoxia, a major component of the tumor microenvironment." (PMID 37264315, 2023). "Here we investigate the effect of antagonizing NPY1R and NPY5R isoforms on MAPK signaling, cell migration, cell proliferation and invasion, in 2D and 3D models of hypoxic and normoxic MCF7 and MDA-MB-231 breast cancer cell lines." (PMID 37264315, 2023). "Neuropeptide Y (NPY) is an abundant neurohormone in human breast carcinomas that acts on a class of G-protein coupled receptors, of which NPY1R and NPY5R are the most highly expressed." (PMID 37264315, 2023). "Immunofluorescence analyses of breast tumour and normal tissue was conducted to determine correlation between NPY1R or NPY5R protein levels and a marker of hypoxia (CAIX) in breast carcinoma." (PMID 37264315, 2023). "Recently, our group demonstrated that NPY1R and NPY5R mRNA abundance is induced by the HIFs, sensitizing hypoxic cells to NPY-stimulated motility and proliferation in MCF7 and MDA-MB-231 breast cancer cells." (PMID 37264315, 2023). "NPY5R is known to induce proliferation via MEK in cardiomyocytes, bone marrow stromal cells and breast cancer cells, and STAT3 in vascular smooth muscle cells." (PMID 31915051, 2020). "For example, two breast cancer cell lines MDA-MB-231 and MCF-7 exhibit increased motility and invasion in response to NPY, which could be blocked with pharmacological NPY1R and NPY5R antagonists." (PMID 40073121, 2025). "Furthermore, breast cancer cell lines such as MDA-MB-231 and MCF7 have elevated levels of NPY1R and NPY5R." (PMID 37264315, 2023). "Additionally, an antagonist of NPY5R blocked NPY-induced granulosa cell proliferation in EA, as also demonstrated in neuroblastoma and breast cancer cells." (PMID 31915051, 2020).
Anxiety (4 papers, 2017 to 2023). Intense feelings of nervousness, tension, or panic often arise in response to interpersonal stresses. "Using TargetScan 6.2 and Diana microT-CDS, in silico prediction yielded high scores for 3’UTR binding of hsa-miR-579-3p for GLRB, HTR2B, and NPY5R, in line with regulation of possible anxiety candidate genes." (PMID 30341278, 2018). "On the other hand, NPY5R effects on fear and anxiety behaviors have been reported in rats." (PMID 36454218, 2023).
breast tumor (2 papers, 2021 to 2023). "In breast tumor tissue compared to normal samples, we show that high NPY5R levels correlate with advanced stage cancer, metastasis, and poorly differentiated cells." (PMID 37264315, 2023). "In human breast tumor tissue, we show that high NPY5R levels correlated with advanced stage cancer, metastasis, and poorly differentiated cells." (PMID 37264315, 2023). "In human breast tumor tissue, we show via immunofluorescence that NPY5R protein levels and colocalization with hypoxia correlate with advanced cancer, and NPY1R protein correlates with adverse outcomes." (PMID 37264315, 2023). "Ectopic expression of NPY5R significantly curbed breast tumor cell growth, induced cell apoptosis and G2/M arrest." (PMID 35087836, 2021).
prostate carcinoma (2 papers, 2012 to 2025). A carcinoma that arises from epithelial cells of the prostate gland. "Last, immunohistochemical analysis of human patients with prostate cancer found that NPY, NPY1R, NPY2R, and NPY5R expression was all significantly increased at the invasive border relative to the bulk tumor mass." (PMID 40073121, 2025).
epilepsy (1 paper, 2024). A brain disorder characterized by episodes of abnormally increased neuronal discharge resulting in transient episodes of sensory or motor neurological dysfunction, or psychic dysfunction. "Based on the literature and database searches, there is association with seizures or epilepsy for five of the brain expressed genes (Marchf1, Tma16, Npy1r, Npy5r, Psd3)." (PMID 38862622, 2024).
glioblastoma (1 paper, 2025). The most malignant astrocytic tumor (WHO grade IV). "The neuropeptide-related genes, including PPY and members of the NPY family (e.g., NPY, NPY1R, NPY2R, NPY4R, NPY5R, PYY), form a distinct cluster characterized by strong co-expression and shared pathway interactions, indicating a potential role in neuroendocrine signaling relevant to glioblastoma." (PMID 40725410, 2025).
lung carcinoma (1 paper, 2025). "We found that brain metastatic lesions of lung cancer exhibited significantly higher expression of the NPY5R (Y5R) compared to other NPY receptors, and the expression of Y5R was selectively enriched in metastatic lung cancer, in contrast to metastatic breast and melanoma cancer." (PMID 40595538, 2025).
lymph node metastasis (1 paper, 2021). "In addition, tumors with high NPY5R methylation had significantly lymph node metastasis (N3 vs. N1, p < 0.05), depth of invasion (T3 vs. T1, p < 0.01), and higher TNM stage (III vs. I/II, p < 0.05)." (PMID 35087836, 2021). "Furthermore, we analyzed the correlations of NPY5R expression and methylation with clinicopathological features, and found that decreased NPY5R expression was correlated with lymph node metastasis (N1 vs. N0, p = 0.04) and depth of invasion (T4/T2 vs. T1, p < 0.05)." (PMID 35087836, 2021).
metastatic cancer (1 paper, 2023). A carcinoma which has spread from the original site of growth to another anatomic site. "We observed higher colocalization between NPY5R and CAIX (7.16-fold) in metastatic cancer compared to non-metastatic cancer." (PMID 37264315, 2023). "Further, there was a higher overall protein expression of NPY5R (2.30-fold) and CAIX (2.12-fold), but not NPY1R, in metastatic cancer relative to non-metastatic cancer." (PMID 37264315, 2023).
migraine (1 paper, 2022). "Other receptors with possible indirect effects on migraine are parathyroid hormone 1 receptor (PTH1R) and PTH2R, which mediates calcium and phosphate homeostasis, and NPY5R that acts as receptor for neuropeptide Y (NPY), PYY, and PYY, and influences eating." (PMID 35453627, 2022).
panic disorder (1 paper, 2022). An anxiety disorder characterized by multiple unexpected panic attacks with persistent concern of recurring attacks. "Some researchers have tried to determine the genetic basis of panic disorder, and some suggestive associations have been observed in several loci, such as BDKRB2 or NPY5R, with this disorder." (PMID 36231907, 2022).
type 2 diabetes mellitus (1 paper, 2022). A type of diabetes mellitus that is characterized by insulin resistance or desensitization and increased blood glucose levels. "NPY and receptors NPY1-R, NPY2-R, and NPY5-R appear to be involved in the pathophysiology of several diseases including diabetes mellitus, heart failure, arterial hypertension and peripheral arterial disease." (PMID 35213955, 2022).
tumor (4 papers, 2021 to 2025). "IHC further confirmed that NPY5R protein levels in BC tissues were lower than those in adjacent non-tumor tissue." (PMID 35087836, 2021). "A significantly decreased NPY5R expression was observed in tumor tissues compared with tumor-free tissues." (PMID 35087836, 2021). "A series of in vitro functional experiments revealed that NPY5R possesses a tumor-suppressive function in BC." (PMID 35087836, 2021). "We further found that NPY5R was frequently downregulated in BC tissues compared with adjacent tumor-matched control tissues, due to its aberrant promoter CpG methylation which was confirmed by methylation analysis and treatment with demethylation agent." (PMID 35087836, 2021). "Collectively, our findings indicate that NPY5R functions as a tumor suppressor but was frequently downregulated in BC." (PMID 35087836, 2021). "The divergent effects of NPY5R on tumor cell proliferation may depend on the tumor cell line used, the NPY5R expressed in the cell line, and different experimental conditions such as different NPY5R concentrations." (PMID 35087836, 2021). "NPY1R did not colocalize more with hypoxic tumor regions across cancer stages, but NPY5R significantly colocalized with hypoxia in stage T3 tumors by 6.53-fold relative to normal breast tissue." (PMID 37264315, 2023). "Furthermore, we also showed that all (7/8 cases) of BC tissues (tumor) exhibited lower NPY5R expression compared to their corresponding non-cancerous controls (normal) by qPCR." (PMID 35087836, 2021).
cancer (3 papers, 2021 to 2025). A tumor composed of atypical neoplastic, often pleomorphic cells that invade other tissues. "Together, these data warrant that the potential of NPY5R as a diagnostic and prognostic marker in cancer treatment." (PMID 35087836, 2021). "One gene (NPY5R) that has rarely been reported among most cancers ranked at the top of the list according to the prognostic importance." (PMID 35087836, 2021). "Furthermore, in NB, NPY has been shown to promote cell motility via increased cytoskeleton remodeling, and NPY5R expression was significantly up-regulated in NB cells adjacent to blood vessels, suggesting preferential NPY5R expression in angioinvasive cancer cells." (PMID 40073121, 2025). "Total NPY1R protein did not significantly change between normal and cancer tissue, however both NPY5R and CAIX protein were higher in stages 2–4 relative to normal tissue with significant 6-fold increases in stage T2." (PMID 37264315, 2023). "NPY5R levels were not a predictor of lower progression-free survival in either cancer subtype." (PMID 37264315, 2023).
Metabolic Disorders (1 paper, 2022). "We studied the association of the single-nucleotide variants (SNVs) rs11100494 and rs6837793 of the NPY5R gene, and rs16147, rs5573, rs5574 of the NPY gene, with metabolic disorders in Russian patients with SSDs." (PMID 35213955, 2022).
NPY5R also shares sentences with these, for which no sentence is quoted: depression (3 papers); Ewing sarcoma (2); Abdominal obesity (1); clear cell renal cell carcinoma (1); glucose metabolism disorder (1); Hypertension (1); Insulin resistance (1); lung adenocarcinoma (1); neuroblastoma (1).